PCSK9 (proprotein convertase subtilisin/kexin type 9)
Diseases named in the same sentence as PCSK9 in open-access papers (continued):
Sharing a sentence is not in itself a finding about the gene and the disease.
COVID-19 (continued). "The PCSK9 expression of peripheral blood mononuclear cells was found to be induced in COVID-19 patients." (PMID 37515197, 2023). "This study provides compelling evidence that PCSK9 inhibitors directly control inflammation in COVID-19." (PMID 38093957, 2023). "The overlap in the plasma levels of PCSK9 between the COVID-19 patients and the non-COVID-19 patients was nearly 95%." (PMID 37515197, 2023). "Research focused on the potential use of PCSK9 inhibitors as an adjuvant therapy in COVID-19 patients has given promising results." (PMID 36140421, 2022). "We argue that in FH patients with COVID-19 the clinicians need even consider intensifying statin therapy as well as the addition of other lipid-lowering agents, such as ezetimibe and PCSK9 inhibitors." (PMID 34622243, 2021). "We have recently pointed to the potentially beneficial effects of cholesterol-lowering therapy in preventing endothelial dysfunction and thrombotic events in HeFH patients with COVID-19, particularly when a statin is combined with a PCSK9 inhibitor." (PMID 34722654, 2021). "We aimed to assess the causal effect of lipid-lowering drugs (HMGCR inhibitiors, PCSK9 inhibitiors, and NPC1L1 inhibitior) on COVID-19 outcomes using two-sample Mendelian randomization (MR) study." (PMID 34866576, 2021). "Circulating PCSK9 levels are elevated in patients with severe COVID-19, and its high expression in hepatocytes may indicate induction of PCSK9 synthesis in the liver." (PMID 41233786, 2025). "The role of PCSK9 blockage as a therapeutic approach for severe COVID-19 thus needs further study." (PMID 39408818, 2024). "The lack of an association of serum PCSK9 with adiposity in SARS-CoV-2 infection indicates no major role of BMI for serum PCSK9 levels in COVID-19." (PMID 39051245, 2024). "Hence, cholesterol-lowering statins, proprotein convertase subtilisin/kexin type 9 antibodies, and ezetimibe have revealed potential to protect against COVID-19." (PMID 38388172, 2024). "In patients with COVID-19 and liver cirrhosis, PCSK9 and six CE species were reduced." (PMID 39051245, 2024). "Indeed, better outcomes of severely ill COVID-19 patients treated once with the PCSK9 inhibitor evolocumab were reported." (PMID 39408818, 2024). "Moreover, in septic patients with coronavirus disease 2019 (COVID-19) with a more severe inflammatory response, PCSK9 levels are further elevated." (PMID 37904138, 2023). "Septic COVID-19 patients had the highest plasma PCSK9 levels, meaning therefore that systemic PCSK9 may become a novel biomarker for SARS-CoV-2 infection." (PMID 37515197, 2023). "Plasma levels of PCSK9 were, however, not found to be associated with death in a cohort of hospitalized COVID-19 patients." (PMID 37515197, 2023). "Notably, a single subcutaneous injection of the monoclonal PCSK9 antibody evolocumab reduced the need for intubation and/or mortality and lowered serum interleukin (IL)-6 in patients with severe COVID-19." (PMID 37515197, 2023). "In that context, very recently it was reported that hospitalized COVID-19 patients receiving a single subcutaneous injection of the PCSK9-mAb evolocumab exhibited reduced death or need for intubation, as well as decreased inflammatory cytokine IL-6 levels in severe COVID-19 cases." (PMID 36851576, 2023). "Suggestive evidence was observed regarding the negative association between PCSK9 expression and risk of COVID-19 susceptibility (OR = 0.84, 95% CI = 0.73–0.97; p = 0.02)." (PMID 34866576, 2021). "We argue that in FH patients with COVID-19 the clinicians need even consider intensifying statin therapy as well as the addition of other lipid-lowering agents, such as proprotein convertase subtilisin/kexin type 9(PCSK9) inhibitors." (PMID 34622243, 2021).
COVID-19 (continued). "Moreover, SREBF2 mRNA, sestrin 1 (SESN1), and proprotein convertase subtilisin/kexin type 9 (PCSK9) RNA levels were increased in PBMCs in COVID-19 patients in a severity-dependent manner." (PMID 34944005, 2021). "Therefore, we advocate using a PCSK9 inhibitor in hospitalized HeFH patients with COVID-19, particularly those with an elevated Lp(a) level and a history of an ACS." (PMID 34722654, 2021). "We found a suggestive evidence of the negative association between PCSK9 expression and COVID-19 susceptibility, but which was not supported when using LDL cholesterol GWAS as an instrument." (PMID 34866576, 2021). "Therefore, we performed two-sample MR analysis in this study to test the association of lipid‐lowering drugs (HMGCR inhibitiors, PCSK9 inhibitiors, and NPC1L1 inhibitior) with COVID-19 outcomes (susceptibility, hospitalization and very severe disease)." (PMID 34866576, 2021). "However, according to the analysis, the mRNA expression levels of SESN1 and PCSK9, that suppress the lipid biosynthesis, were increased in the PBMCs of COVID-19 patients." (PMID 32883951, 2020). "In addition, PCSK9 has functions beyond the regulation of serum cholesterol levels that could be relevant for COVID-19 severity." (PMID 39408818, 2024). "Moreover, interleukin-6 levels were lower in COVID-19 patients randomized to PCSK9 inhibitors." (PMID 37158917, 2023). "In the subgroup of patients with liver cirrhosis, only two patients had COVID-19, and associations of PCSK9 levels with viral infection could not be analyzed." (PMID 37515197, 2023). "The cell type which contributes to plasma PCSK9 in COVID-19 is unknown as of yet." (PMID 37515197, 2023). "PCSK9 may be associated with viral infectious diseases, including hepatitis C virus (HCV), dengue fever virus (DENV), and SARS-CoV-2, the etiological agent of COVID-19." (PMID 36230934, 2022). "Therefore, the use of PCSK9 inhibitors in the treatment of COVID-19 may be another potential strategy." (PMID 36230934, 2022). "Although the cholesterol metabolism pathway was significantly downregulated (including APOA2, APOC1, APOH, CETP, and APOA4), the increased levels of PCSK9 and APOB suggested the dysregulation of cholesterol metabolism in severe and critical COVID-19 patients." (PMID 35958562, 2022). "We confirmed that SREBP-2-induced cholesterol biosynthesis was suppressed by Sestrin-1 and PCSK9 expression, while the SREBP-2-induced inflammatory responses was upregulated in COVID-19 ICU patients." (PMID 32883951, 2020). "Antibody levels were not correlated with PCSK9, and the negative correlation of CE species with antibody levels in patients with severe COVID-19 seems to be related to disease severity." (PMID 39051245, 2024). "PCSK9 did not correlate with the BMI in the moderate COVID-19 group (r = −0.084, p = 0.732) and in the severe COVID-19 cohort (r = −0.027, p = 0.847)." (PMID 39051245, 2024). "Most CE species with shorter fatty acid chains were decreased in severe compared to moderate COVID-19, and none of the CE species were correlated with PCSK9 in patients with severe COVID-19." (PMID 39051245, 2024). "Plasma PCSK9 levels did not correlate with survival in hospitalized COVID-19 patients and in septic patients with COVID-19 in accordance with the current findings." (PMID 39051245, 2024). "Previous research has demonstrated that plasma PCSK9 levels are elevated in septic patients with COVID-19 compared to septic patients without SARS-CoV-2 infection." (PMID 39051245, 2024). "The beneficial effects of PCSK9 blockage in patients with severe COVID-19 can not be explained by a strong increase in PCSK9 in severe COVID-19 cases because the levels between severe and moderate cases did not greatly differ." (PMID 39051245, 2024).
COVID-19 (continued). "PCSK9 did not correlate with any of the CE species, total CE levels, or FC in severe COVID-19 (p > 0.05 for all)." (PMID 39051245, 2024). "Serum PCSK9 was not related to the need for dialysis in the moderate (3 patients, p = 0.872) and severe (7 patients, p = 0.271) COVID-19 patients." (PMID 39051245, 2024). "PCSK9 did not correlate with the patient’s age in the moderate COVID-19 group (r = 0.242, p = 0.161) and the severe COVID-19 cohort (r = −0.093, p = 0.485)." (PMID 39051245, 2024). "When patients with COVID-19 and liver cirrhosis were excluded, plasma PCSK9 did not correlate with the CRP, leukocyte count, or procalcitonin." (PMID 37515197, 2023). "Overlap in the PCSK9 levels of the COVID-19 patients and the non-COVID-19 patients made it difficult to establish the cut-off values, and therefore, studies on larger cohorts are needed." (PMID 37515197, 2023). "Eleven patients with liver cirrhosis died (without patients with COVID-19), and their plasma PCSK9 levels was also comparable to the patients who survived (p = 0.497)." (PMID 37515197, 2023). "PCSK9 in the plasma of 84 patients (without patients with COVID-19 and patients with liver cirrhosis) who survived and 18 patients who died was determined to be similar (p = 0.243)." (PMID 37515197, 2023). "IVW-MR analysis did not provide any evidence for the association between PCSK9-mediated LDL cholesterol and COVID-19 outcomes." (PMID 34866576, 2021). "Furthermore, to the best of our knowledge, no study has analyzed the serum levels of PCSK9 and cholesterol in COVID-19 patients simultaneously." (PMID 39051245, 2024). "Notably, there was a strong induction of systemic PCSK9 levels in patients with moderate COVID-19 disease that did not increase much further in severe COVID-19 cases." (PMID 39408818, 2024). "Inhibitors of proprotein convertase subtilisin kexin type 9 (PCSK9), such as the monoclonal antibodies alirocumab and evolocumab, represent another class of lipid-lowering agents shown to suppress DENV replication in vitro and reduce mortality and inflammation in severe COVID-19 patients." (PMID 37259914, 2023). "When appropriate, PCSK9 inhibition may be included in the lipid-lowering therapy even among younger FH patients with COVID-19 and thereafter, as, unlike statins, the PCSK9 inhibitors can also reduce the level of serum Lp(a)." (PMID 35645833, 2022). "However, plasma SREBP-2 protein levels were similar in patients with and without COVID-19, and thus may not contribute to higher plasma PCSK9." (PMID 41233786, 2025). "Interestingly, serum PCSK9 correlated with viral titer in moderate but not severe COVID-19." (PMID 39051245, 2024). "Plasma PCSK9 levels of the COVID-19 patients did not correlate with C-reactive protein (CRP), procalcitonin, IL-6, ferritin, or leukocyte count, illustrating that, at least in SARS-CoV-2 infection, higher PCSK9 is not simply a marker of inflammation." (PMID 39051245, 2024).
endothelial dysfunction (42 papers, 2015 to 2025). In vascular diseases, endothelial dysfunction is a systemic pathological state of the endothelium (the inner lining of blood vessels) and can be broadly defined as an imbalance between vasodilating and vasoconstricting substances produced by (or acting on) the endothelium. "Oxidative stress is a major contributor to endothelial dysfunction and AS, andgrowing evidence supports a strong association between PCSK9 and endothelialoxidative stress." (PMID 41209111, 2025). "A study involving patients with ST-elevation myocardial infarction revealed a strong association between PCSK9 levels and endothelial dysfunction, assessed through the rate of apoptosis in HUVECs." (PMID 40354375, 2025). "In said context, PCSK9 deficiency reduces endothelial dysfunction by reducing the expression of lower endothelial expression of the genes encoding, e.g., ICAM-1, CCL2, IL-6 and IL-1β." (PMID 36361853, 2022). "Our previous data have shown that PCSK9 caused inflammatory stress and endothelial dysfunction, and that the pleiotropic protective effects of i-PCSK9 in EC might be mediated, at least in part, by NAD-dependent deacetylase SIRT3." (PMID 37587410, 2023). "Moreover, PCSK9 has been implicated in endothelial dysfunction by upregulating the expression of intercellular adhesion molecule-1 (ICAM-1) and vascular cell adhesion molecule-1 (VCAM-1) in endothelial cells." (PMID 34336112, 2021). "By affecting processes such as VSMC and endothelial dysfunction, cellular senescence, and vascular inflammation, PCSK9 plays a multifaceted role in vascular aging and the pathogenesis of vascular diseases." (PMID 40354375, 2025). "Inflammation and endothelial dysfunction often trigger lipid metabolism disorders, which increase the expression of PCSK9 as an adaptive response." (PMID 40699832, 2025). "Experimental studies have demonstrated that silencing or inhibiting endothelial PCSK9 alleviates endothelial dysfunction, reduces plaque development, and mitigates inflammatory responses." (PMID 41209111, 2025). "Inhibition of PCSK9 has also been shown to reduce endothelial dysfunction and the size of atherosclerotic lesions, suggesting a potential therapeutic target for the treatment of atherosclerotic diseases." (PMID 40354375, 2025). "Evidence suggests that inhibiting PCSK9 can mitigate endothelial dysfunction and reduce the size of atherosclerotic lesions, offering a promising avenue for therapeutic interventions in atherosclerotic diseases." (PMID 40354375, 2025). "The study concluded that PCSK9 inhibition reduced markers of platelet activation and endothelial dysfunction in ACS patients." (PMID 41478627, 2025). "A clinicalstudy reported that inhibition of PCSK9 significantly reduced biomarkers ofplatelet activation and endothelial dysfunction in patients with acute coronarysyndrome (ACS)." (PMID 41209111, 2025). "While primarily used for its LDL-reducing capacities, PCSK9 inhibitors, much like SGLT2is, exhibit pleiotropic effects, including the attenuation of inflammation, reactive oxygen species (ROS), and endothelial dysfunction." (PMID 39268545, 2024).
endothelial dysfunction (continued). "While primarily used to reduce low-density lipoprotein, PCSK9 inhibitors exhibit pleiotropic effects, including the attenuation of inflammation, reactive oxygen species, and endothelial dysfunction." (PMID 39268545, 2024). "We review the effect of PCSK9 inhibitors on various mechanisms involving platelet activation, inflammation, endothelial dysfunction, and the resultant clot formation." (PMID 37765005, 2023). "Thirdly, PCSK9 is correlated with activation of macrophage, inflammation,and endothelial dysfunction within plaques." (PMID 39076402, 2023). "The data revealed that functional PCSK9 inhibition reduces systemic inflammation and endothelial dysfunction by constraining leukocyte–endothelium interactions." (PMID 36768292, 2023). "It appears that PCSK9 inhibitors also influence platelet function, inflammation, and endothelial dysfunction." (PMID 37765005, 2023). "Several studies have shown the effect of PCSK9 inhibitors on endothelial function and the correlation between PCSK9 and endothelial dysfunction." (PMID 37765005, 2023). "In vivo and ex vivo analyses proved that PCSK9 inhibitors impair endothelial dysfunction by limiting interactions among leukocytes and endothelium." (PMID 37765005, 2023). "Mechanistic studies uncovered that SOX17 promoted transcription and release of miR‐224‐5p and miR‐361‐3p, thereby targeting NR4A3 and PCSK9 to improve endothelial dysfunction." (PMID 36919784, 2023). "Regarding the mechanism, PCSK9 plays multiple immune roles in platelet aggregation, adhesion to endothelial cells, and endothelial dysfunctions." (PMID 37959416, 2023). "Therefore, this study aimed to investigate the potential of PCSK9 inhibitor therapy to alleviate inflammation and endothelial dysfunction in the early phase of AMI by measuring TNF-α levels and the L-arginine/ADMA ratio." (PMID 39368019, 2025). "However, the impact of PCSK9 inhibitors on inflammation and endothelial dysfunction in the early phase of AMI remains to be elucidated." (PMID 39368019, 2025). "The improvement in endothelial function could be attributed to several mechanisms: PCSK9 inhibitors' ability to lower LDL-C levels can mitigate endothelial cell damage caused by elevated LDL-C, thereby preventing endothelial dysfunction." (PMID 39650150, 2024). "Finally, our study group is unique also because of the evaluation of the relationship of PCSK9 concentration, markers of endothelial dysfunction, inflammation, and rheologically important parameters to the AMD prognosis." (PMID 39572693, 2024). "Potential explanations for this discordance between patient genotype and serum protein concentrations with endothelial dysfunction markers include although 90% of circulating PCSK9 is secreted by the liver, another major source of PCSK9 is vascular smooth muscle cells." (PMID 37365661, 2023). "In the future, patients could benefit from the monitoring of PCSK9 levels in serum because of the connection between platelet activation and endothelial dysfunction." (PMID 37765005, 2023). "Finally, add-on treatment with PCSK9 inhibitors showed increased plasma levels of miRNAs participating in cholesterol metabolism (miR-122 and miR-27a), endothelial dysfunction (miR-126 and mir-26a), and inflammation (miR-92a, miR-155, and miR-125a)." (PMID 37628623, 2023). "Interestingly, PCSK9 was more abundant in HDL3 of T1D especially in those with HbA1c values ≥ 8.5% and its amount in HDL2 was associated with endothelial dysfunction." (PMID 36899434, 2023).